HOXA5 (homeobox A5)
Diseases named in the same sentence as HOXA5 in open-access papers (continued):
Sharing a sentence is not in itself a finding about the gene and the disease.
Obesity (continued). "In our findings, the HOXA5 gene in the control patient group was hypermethylated, favoring its transcription and translation, thereby acting as a protective factor against the development of obesity in patients treated with growth hormone." (PMID 40564006, 2025). "Indeed, Hoxa5 alleviates obesity-induced chronic inflammation by promoting M2 macrophage polarization in mouse AT." (PMID 37626900, 2023). "A similar strategy could be used to reduce the HOXA5 promoter methylation in order to restore its function and restrain AT dysfunction in obesity." (PMID 37626900, 2023). "It is also possible that the HOXA5 transcription factor may control inflammation, such that its decreased AT expression during obesity may release the brake on pro-inflammatory genes, limiting tissue repair capability." (PMID 37626900, 2023). "Nonetheless, recent evidence supports the hypothesis of a role for HOXA5 in metabolic diseases, particularly in obesity and type 2 diabetes (T2D)." (PMID 37626900, 2023). "Given the critical role of HOXA5 in promoting the M2 macrophage switch in chronic inflammation, targeting its immunomodulatory action may provide therapeutic benefits and alleviate obesity-related inflammation and metabolic abnormalities." (PMID 37626900, 2023). "As a crucial regulator of adipose cell development, HOXA5 is required for proper lipid storage in the AT and may thus contribute to obesity." (PMID 37626900, 2023). "Animal studies, where we and others have demonstrated that the expression of HOXA5 was significantly reduced in the abdominal fat depots of diet-induced and genetically obese mice, provide additional evidence for the role of HOXA5 in the pathophysiology of obesity." (PMID 37626900, 2023). "So far, the function of Hoxa5 in obesity‐induced chronic inflammation has been poorly understood." (PMID 31441588, 2019). "In addition, the authors have shown that one of these developmental genes (HOXA5) exhibit changes in expression that closely correlate with the extent of obesity (BMI) and the pattern of fat distribution (WHR)." (PMID 28231762, 2017). "Besides, individuals who have obesity and T2D showed reduced expression of HOXA5 in abdominal SAT." (PMID 37626900, 2023). "Therefore, Hoxa5 may be a potential molecular target for obesity and related metabolic disturbances." (PMID 37626900, 2023). "Some researchers have found that in epididymal adipose tissue of mice fed with a high-fat diet (HFD), Hoxa5 undergoes dynamic DNA methylation and transcriptional repression, which may represent a potential way to quantify obesity response to nutritional intervention." (PMID 29221131, 2017). "Interestingly, replacing HFD with a standard chow diet improves the metabolic phenotype while also restoring normal DNA methylation and expression levels at Hoxa5, suggesting that the Hoxa5 methylation pattern may reflect the obesity response to nutritional intervention." (PMID 37626900, 2023). "A downregulation of HOXA5 was also observed in isolated adipocytes from the abdominal SAT of obese Pima Indians, a population with one of the highest prevalence rates of obesity and T2D." (PMID 37626900, 2023). "Therefore, the HOXA5 deficit is a distinct feature of a dysfunctional abdominal SAT and may represent a marker of an increased risk of developing unfavorable metabolic outcomes, either in individuals with T2D familiarity or in subjects with obesity." (PMID 37626900, 2023). "Hoxa5 attenuates ER stress by inhibiting the eIF2α/PERK signaling pathway in adipocytes and promotes M2 macrophage polarization, and which in turn attenuates obesity-induced chronic inflammation." (PMID 38509524, 2024). "Additionally, Hoxa5 transcriptionally activated the PPARγ pathway to promote alternative activation of macrophage and WAT browning, which in turn alleviated obesity-induced chronic inflammation." (PMID 37153549, 2023).
Obesity (continued). "Thus, to further investigate the relationship between a HOXA5 deficit and dysfunctional SAT, we expanded our analysis and explored published large-scale human obesity expression profile datasets." (PMID 35203377, 2022). "Accordingly, we explored whether the HOXA5 epigenetic profile was affected in blood samples of FDR and/or obesity subjects." (PMID 35203377, 2022). "Therefore, we explored the intrinsic link between Hoxa5, ERS, chronic inflammation and M2 macrophage polarization to provide a theoretical basis for the treatment of obesity." (PMID 31441588, 2019).
cervical cancer (12 papers, 2014 to 2025). A primary or metastatic malignant neoplasm involving the cervix. "The downregulation of HOXA5 is associated with poorly differentiated cervical cancer, and HOXA5 is downregulated in grade 1 EC." (PMID 37834206, 2023). "In these reports, HOXA5 overexpression was associated with a better prognosis in cervical cancer." (PMID 37834206, 2023). "Some studies have shown a relationship between aberrant HOXA5 gene expression and gynecologic cancers, such as cervical cancer and EC." (PMID 37834206, 2023). "In cervical cancer, Hoxa5 inhibited the proliferation and tumor formation through repression the activity of Wnt/β-catenin pathway." (PMID 35883405, 2022). "More recently, it was further reported that the ectopic expression of HOXA5 suppressed proliferation and neoplasia in cervical cancer cells by repressing Wnt signaling." (PMID 35203377, 2022). "Consistent with our findings, the overexpression of Hoxa5 in cervical cancer markedly inhibited cell proliferation through protein p27 and kinase B." (PMID 35883405, 2022). "The expression of HOXA5 protein in cervical cancer cell lines was evaluated by western blot and immunochemistry." (PMID 32499530, 2020). "In the present research, both the data from clinical specimens and the data from the GEO database indicated that the expression of HOXA5 protein was downregulated in cervical cancer." (PMID 32499530, 2020). "The results showed that the proliferation-inhibiting ability of HOXA5 in cervical cancer cells was partly abolished upon overexpression of β-catenin in both HOXA5-overexpressing HeLa and SiHa cells." (PMID 32499530, 2020). "Altogether, these findings demonstrate that HOXA5 inhibits the proliferation of cervical cancer cells in vitro." (PMID 32499530, 2020). "In particular, the upregulation of the HOXA1, HOXA5, and HOXA6 genes were found to be significantly associated with unfavorable overall survival in patients with cervical cancer." (PMID 29137433, 2017). "In this study, we showed that the increased mRNA expression of four HOX genes—HOXA1, HOXA5, HOXA6, and HOXC11—is independently associated with mortality in cervical cancer based on data from TCGA." (PMID 29137433, 2017). "All these data indicate that HOXA5 suppressed the expression of cyclinD1 by inhibiting the activity of the Wnt/β-catenin signaling pathway through inhibition of the nuclear translocation of the β-catenin protein in cervical cancer." (PMID 32499530, 2020). "Thus, we tested the effect of activating the Wnt/β-catenin pathway in HOXA5-modified cervical cancer cells via transient transfection of the β-catenin plasmid." (PMID 32499530, 2020). "In conclusion, in this study, we showed that the upregulation of the expression of the HOXA1, HOXA5, and HOXA6 genes are significantly associated with unfavorable overall survival as well as increased mortality in a large cohort of cervical cancer cases from TCGA database." (PMID 29137433, 2017). "Upregulated HOXA1, HOXA5, and HOXA6 expression are significantly correlated with unfavorable overall survival and increased mortality in cervical cancer patients." (PMID 29137433, 2017).
cervical cancer (continued). "Another report demonstrated that HOXA5 could suppress the proliferation and invasion and induce apoptosis through AKT and p27 in cervical cancer cells." (PMID 32499530, 2020).
colon cancer (12 papers, 2004 to 2025). "Furthermore, HOXA5 is downregulated in colon cancer, and its re-expression induces loss of the cancer stem cell phenotype, preventing tumor progression and metastasis." (PMID 34445617, 2021). "Bioinformatics analysis of colon cancer datasets revealed that HOXA5 was significantly downregulated in both colorectal adenoma and carcinoma when compared to normal colon tissue." (PMID 39858044, 2025). "HOXA5 expression in colon cancer cell lines induced terminal differentiation and epithelial morphology instead of a stem cell phenotype." (PMID 39858044, 2025). "HOXA5, a paralog of HOXA10, has previously been reported to be down-regulated in colon cancer cells and its re-expression induces loss of the cancer stem cell phenotype, thereby preventing tumor progression and metastasis." (PMID 31763673, 2019). "To confirm the mitotic potential of the HOXA5 short RNA, we established three different colon cancer cell lines that stably expressed the HOXA5 short RNA transcript using HCT116, DLD1, and HT-29 cells." (PMID 31159758, 2019). "We found novel transcripts from HOXA5 in human colon cancer HCT116 cells using a next generation sequencing-based targeted RNA capture system." (PMID 31159758, 2019). "We identified three novel transcripts (HOXA5 short, long 1, and long 2) transcribed from the HOXA6-HOXA5 locus in HCT116 colon cancer cells using next generation sequencing-based targeted mRNA capture." (PMID 31159758, 2019). "Although further studies are needed to fully define the role of HOXA5 short RNA in the process of colon cancer, this study provides new insight into the potential role of HOXA5-derived functional RNAs in colon cancer growth." (PMID 31159758, 2019). "Stable overexpression of HOXA5 short RNA promoted proliferation and migration of colon cancer cell lines HCT116, DLD1, and HT-29 and accelerated tumor growth in the xenograft mouse model." (PMID 31159758, 2019). "HOXA5 plays a similar role in colon cancer, as silencing of HOXA5 by Wnt signaling maintains the pool of CSC and reactivation of HOXA5 by RA treatment induces loss of the CSC." (PMID 30974862, 2019). "HOXA5 short RNA was highly expressed in colon cancer cells and advanced colon cancer tissues, suggesting that HOXA5 short RNA plays an oncogenic role." (PMID 31159758, 2019). "Here, we identified a novel lncRNA (named HOXA5 short RNA) transcribed from the HOXA6-HOXA5 locus in human colon cancer cells using a next generation sequencing-based RNA capture system." (PMID 31159758, 2019). "HOXA5 expression is reported to be suppressed in poorly differentiated colon cancer cells, such as HCT116 cells." (PMID 31159758, 2019). "Additionally, the expression of HOXA5 short RNA relative to HOXA5 mRNA was increased in advanced colon cancer tissues (P = 0.0126)." (PMID 31159758, 2019). "To further investigate the potential clinical relevance of HOXA5 short RNA in tumor development, we measured the expression of both HOXA5 short RNA and coding HOXA5 mRNA in cDNA libraries prepared from 21 patients with colon cancer (HCRT103; OriGene, Rockville, MD, USA)." (PMID 31159758, 2019). "Our results suggested that HOXA5 short RNA, a novel lncRNA, may play a crucial role in colon tumor growth through activation of EGF signaling." (PMID 31159758, 2019). "Interestingly, knockdown of HOXA5 inhibits cellular differentiation in retinal-treated colon tumors, suggesting that HOXA5 is a candidate master regulator of intestinal differentiation in colon cancer." (PMID 28678194, 2017). "Furthermore, we provide evidence that HOXA5 short RNA may have activated EGFR signaling in both colon cancer cell lines and xenograft tumors." (PMID 31159758, 2019). "The lncRNA HOXA5 short, derived from the HOXA6-HOXA5 locus and upregulated in advanced colon tumors, has been shown to enhance CRC growth in a xenograft mouse model." (PMID 33352769, 2020).
colon cancer (continued). "A recent study showed that HOXA5 promoted differentiation by downregulating WNT signaling in colon epithelial cells and acted as a tumor suppressor in colon cancer tissues." (PMID 31159758, 2019). "In a human colon cancer dataset, HOXA5 expression was lower in carcinomas compared with that in normal colon tissues, and high levels of HOXA5 expression was a prognostic factor for predicting improved relapse-free survival." (PMID 31159758, 2019).
breast tumors (11 papers, 2005 to 2025). "Artesunate, at varying concentrations, also suppressed the protein expression of HOXA5, WNT, β-catenin, Fizz1, and Arg-1, thereby modulating the WNT-β-catenin signaling pathway and ultimately curbing the proliferation of breast tumor cells." (PMID 40758729, 2025). "In addition, in syngeneic mouse breast tumor models and xenotransplantation models, KDM5B knockout leads to upregulation of tumor suppressor genes such as BRCA1, CAV1, and HOXA5 and increased H3K4 methylation in the chromatin regions of these target genes." (PMID 35493099, 2022).
gastric cancer (10 papers, 2012 to 2025). A primary or metastatic malignant neoplasm involving the stomach. "Recently, HOXA5 was found to be the most differentially hypermethylated gene between gastric cancer and tumor-adjacent gastric tissue." (PMID 32736574, 2020). "HOXA5 is highly expressed in gastric cancer cell lines and oral squamous cell carcinomas (OSCC) tissues and cell lines." (PMID 26011628, 2015).
glioma (10 papers, 2017 to 2025). A benign or malignant brain and spinal cord tumor that arises from glial cells (astrocytes, oligodendrocytes, ependymal cells). "On the other hand, Hoxa5 and Fabp4, both associated with increased malignancy in gliomas, were upregulated in MYC/SMARCA4 tumors." (PMID 37919824, 2023). "Increased expression of HOXA5, encoding a transcription factor named homeobox genes, was associated with the tumorigenic potential of glioma stem cell." (PMID 37553713, 2023). "In glioma tissues from the high-risk group of the training cohort, HOXA5, PTPN2, WT1, HOXD10, POSTN, ADAMDEC1 and MYBPH were highly expressed." (PMID 37812190, 2023). "Our multivariate Cox regression analysis indicated that the HOXA5-derived immune signature was independently associated with the outcomes of ATRX-wt glioma patients." (PMID 37812190, 2023). "In conclusion, this work proved that high HOXA5 expression positively correlated with glioma malignancy’s clinical features and was associated with an unfavorable survival outcome." (PMID 34485110, 2021). "In this study, high HOXA5 expression is associated with malignant clinical features like high-grade glioma or IDH wildtype glioma, worse clinical treatment outcome, and strong cells proliferative ability." (PMID 34485110, 2021). "To determine whether HOXA5 expression levels were associated with specific genomic characteristics in gliomas, we performed copy number variation (CNV) and somatic mutation analysis using the TCGA data set." (PMID 34485110, 2021). "Nevertheless, HOXA5, PTPN2, WT1, HOXD10, POSTN, ADAMDEC1 and MYBPH were overexpressed in ATRX-mt glioma tissues with high-risk scores compared with low-risk scores." (PMID 37812190, 2023). "In the test cohort, HOXA5, PTPN2, WT1, HOXD10, POSTN, ADAMDEC1 and MYBPH levels were elevated in glioma tissues with high-risk scores." (PMID 37812190, 2023). "We next assessed the prognostic value of HOXA5 expression in human gliomas using ROC curve analysis and Kaplan-Meier analysis." (PMID 34485110, 2021). "The mRNA expression levels of HOXA5 in different WHO grade gliomas were evaluated using expression data from publicly available databases: TCGA, n = 672; CGGA, n = 1013." (PMID 34485110, 2021). "The HOXA5 levels in common cancer types other than gliomas were further evaluated (P <0.001, respectively)." (PMID 34485110, 2021). "In this work, HOXA5, from the HOX family, was identified as a glioma cell proliferation-associated factor by investigating its feature in the TCGA and CGGA data set." (PMID 34485110, 2021). "HOXA5 was upregulated in CL and ME subtypes by comparing with NE and PN subtypes in pan-glioma analysis in TCGA data set, where CL subtype had the highest expression of HOXA5 (P <0.001)." (PMID 34485110, 2021). "Together, those evidences supported that HOXA5 promoted glioma progression through affecting cell cycle, cell proliferation, and cell apoptosis." (PMID 34485110, 2021). "HOXA5 was observed to be significantly up-regulated in GBM (WHO grade IV) compared with low-grade glioma (LGG) samples (WHO grade III and WHO grade II) in the TCGA and CGGA cohorts (P <0.001, respectively)." (PMID 34485110, 2021). "In cell lines, U87MG and U251, by interfering HOXA5 expression significantly inhibit glioma progression and apoptosis, and cell cycle is arrested at the G2/M phase." (PMID 34485110, 2021). "Collectively, increased HOXA5 expression can promote glioma progression via affecting glioma cell proliferation." (PMID 34485110, 2021). "HOXA5 was upregulated in the IDH mutant gliomas in TCGA data set, in the IDH mutant GBM in TCGA microarray data set, and in both the IDH mutant gliomas and GBM alone in CGGA data set (P <0.001, respectively)." (PMID 34485110, 2021).